ACTN4 (actinin alpha 4)
Diseases named in the same sentence as ACTN4 in open-access papers (continued):
Sharing a sentence is not in itself a finding about the gene and the disease.
memory impairment (2 papers, 2024 to 2025). "Reducing EV secretion, interfering with miR-142-5p expression or overexpressing ACTN4, ELAVL4 and USP9X ameliorated memory impairment and rescued CNP-associated dendritic spine changes." (PMID 38632655, 2024). "Additionally, overexpression of alpha-actinin-4 (ACTN4) has been found to alleviate memory impairment and reverse chronic neuropathic pain-related changes in dendritic spines." (PMID 40227445, 2025). "miR-142-5p was identified as the key molecule responsible for pathological SC-EVs-mediated memory impairment, and α-actinin-4 (ACTN4), ELAV-like protein 4 (ELAVL4, also known as HuD) and ubiquitin-specific peptidase 9 X-linked (USP9X) were identified as novel target molecules of miR-142-5p." (PMID 38632655, 2024).
nasopharyngeal carcinoma (2 papers, 2022 to 2023). A carcinoma arising from the nasopharyngeal epithelium. "Meanwhile, ACTN4 is also involved in the progression of several diseases, including melanoma, hepatocellular carcinoma, nasopharyngeal carcinoma, and ovarian clear-cell adenocarcinomas." (PMID 37626047, 2023). "Through previous literature, it is known that RING finger protein 38 (RNF38) ubiquitinates ACTN4 in nasopharyngeal carcinoma, leading to the degradation of ACTN4 and inhibiting tumor proliferation and metastasis." (PMID 37626047, 2023).
neuroblastoma (2 papers, 2016 to 2020). Neuroblastoma (NB) is the most common solid, extracranial childhood tumor. "In addition to its predicted targeting of MYH9, miR-124-3p was predicted to target additional cytoskeletal genes (PLEC, ITGB1, VIM, and ACTN4) from our panel, which were overexpressed in the resistant SK-N-ASCis24 neuroblastoma cell model." (PMID 33330445, 2020). "These cytoskeletal genes (MYH9, PLEC, ITGB1) and mesenchymal markers (VIM, ACTN4), were previously reported by our lab to be up-regulated with cisplatin resistance development and involved in phenotypic and morphological modulation observed in our neuroblastoma cell model." (PMID 33330445, 2020). "The cytoskeletal genes MYH9, PLEC, ITGB1, VIM, and ACTN4, were previously reported by our lab to drive EMT-like morphological transformation and increased invasiveness (2.5 fold) in the MES SK-N-ASCis24 neuroblastoma cell line, coinciding with resistance development." (PMID 33330445, 2020).
oral squamous cell carcinoma (2 papers, 2014 to 2019). "Also, RNAi-mediated downregulation of ACTN4 showed an association between the over expression of ACTN4 and an aggressive phenotype of oral squamous cell carcinoma." (PMID 25215525, 2014).
preeclampsia (2 papers, 2021 to 2023). Preeclampsia is a hypertensive disorder of pregnancy that is characterized by new-onset hypertension with proteinuria presenting after 20 weeks of gestation, and depending on mild or severe forms may initially present with severe headache, visual disturbances, and hyperreflexia. "Our findings suggest that ACTN4 may act as an important regulator of trophoblast proliferation and differentiation during early pregnancy, and dysregulation of this protein may contribute to preeclampsia pathogenesis." (PMID 33757527, 2021).
acute lymphocytic leukemia (1 paper, 2022). "After 70 months of follow-up, ALPK1, ACTN4, CALR, and ZNF695 were identified as potential prognostic risk factors for adult acute lymphocytic leukemia in the overall survival analysis." (PMID 36139553, 2022). "ALPK1, ACTN4, CALR, ZNF695, and FBXL5 were identified as novel prognostic genes in relapsed acute lymphoblastic leukemia." (PMID 36139553, 2022).
Adult onset (1 paper, 2024). Onset of disease manifestations in adulthood, defined here as at the age of 16 years or later. "The commonest genes affected in adult-onset FSGS (COL4A3–COL4A5,GLA ) have ocular abnormalities but not the other frequently affected genes (ACTN4, CD2AP, INF2, TRPC6)." (PMID 37578539, 2024).
amoebiasis (1 paper, 2025). "Amoebiasis pathways contain ACTN4 protein and arachidonic acid metabolite." (PMID 41153976, 2025). "More interestingly, the amoebiasis was where ACTN4-arachidonic acid interaction enriched." (PMID 41153976, 2025).
arrhythmogenic right ventricular cardiomyopathy (1 paper, 2016). "Besides, some other ones were correlated with arrhythmogenic right ventricular cardiomyopathy (e.g. ACTN4, CTNNA1 and ITGB5), as well as complement and coagulation cascades (e.g. C1R and C1S)." (PMID 27613243, 2016).
Atrophy (1 paper, 2023). Any weakening or degeneration, especially through lack of use. "The ACTN4 mutation caused distinct electron-dense aggregates in podocyte cell bodies, while the COL4A5 mutation led to segmental sclerosis of glomeruli with marked interstitial fibrosis and tubular atrophy." (PMID 38139322, 2023).
bacterial vaginosis (1 paper, 2014). Infection caused by bacterial overgrowth in the vagina. "Therefore, extensive validation of this marker on a larger number of samples, including those from patients suffering from other diseases and infections (HIV, herpes, bacterial vaginosis, Chlamydia etc.), is the next step to determine whether ACTN4 is suitable for diagnosis purposes." (PMID 25215525, 2014).
bladder tumors (1 paper, 2016). "However, another study has reported amplification of the DPF-PPP1R14A-SPINT2-KCNK6 and ACTN4 loci on chromosome 19q13 in human bladder tumors and of the chromosomal region19q13.12-q13.2 in human urothelial carcinomas, especially in invasive types." (PMID 27902773, 2016).
carcinosarcoma (1 paper, 2025). A malignant tumor composed of a mixture of carcinomatous and sarcomatous elements. "The observation that ACTN4 amplification appears to be more frequent in serous carcinoma and carcinosarcoma, which are histological subtypes often associated with the copy‐number high (CN‐H) molecular subtype in TCGA classification." (PMID 41218617, 2025).
cataract (1 paper, 2025). Partial or complete opacity of the crystalline lens of one or both eyes that decreases visual acuity and eventually results in blindness. "Proteins involved in actin and microtubule cytoskeleton organization, including ACTN4, were downregulated in all three cataract groups compared to controls." (PMID 41283652, 2025). "Across all cataract groups, actin and microtubule cytoskeletal proteins (ACTN4, DCTN1, TUBA1C, TBCB, TUBB4A) were significantly downregulated compared to controls, with the most marked suppression in ARC." (PMID 41283652, 2025). "Specifically, proteins including ACTN4, DCTN1, MYO18A, TUBA1C, TBCB, and TUBB4A, were downregulated in all cataract groups compared to controls." (PMID 41283652, 2025).
clear cell ovarian cancers (1 paper, 2008). "Interestingly, enhanced cytoplasmic expression of ACTN4 is observed in about 60% of endometrioid and clear cell ovarian cancers, both of which have been suggested to possibly arise, at least in some cases, from endometriosis." (PMID 19055724, 2008).
dilated cardiomyopathy (1 paper, 2020). Cardiomyopathy which is characterized by dilation and contractile dysfunction of the left and right ventricles. "In addition to Actn1, we observed also a strong expression of Actn4 in cardiomyocytes of patients with dilated cardiomyopathy suggesting similar functions." (PMID 32774516, 2020).
Duchenne muscular dystrophy (1 paper, 2025). Duchenne muscular dystrophy (DMD) is a neuromuscular disease characterized by rapidly progressive muscle weakness and wasting due to degeneration of skeletal, smooth and cardiac muscle. "Here, we report a case of adolescent-onset FSGS with ACTN4 mutation (c.776C > T, p.T259I), diagnosed by genetic testing following a renal biopsy performed for persistent proteinuria observed during treatment for Duchenne muscular dystrophy (DMD)." (PMID 41013435, 2025).
endometriosis (1 paper, 2008). The growth of functional endometrial tissue in anatomic sites outside the uterine body. "ACTN4, which we find strongly expressed in the endometriotic samples, is another candidate gene possibly involved in the pathogenesis of endometriosis." (PMID 19055724, 2008). "Furthermore, since PI3K can control nuclear translocation of ACTN4, activation of the PI3K-Akt pathway in endometriosis may facilitate enhanced cytoplasmic expression of ACTN4, and may contribute the cell motility and invasion observed in endometriosis." (PMID 19055724, 2008). "Because of their expression pattern, SHC1, ACTN4, and AXL, were identified as promising endometriosis-related candidate genes, and their expression patterns were further investigated at the protein level by immunohistochemistry." (PMID 19055724, 2008).
epilepsy (1 paper, 2012). A brain disorder characterized by episodes of abnormally increased neuronal discharge resulting in transient episodes of sensory or motor neurological dysfunction, or psychic dysfunction. "Alpha-actinin-4 (ACTN4) also belongs to the spectrin superfamily playing complementary roles to SPTBN1 and SPTBN2 and has been implicated in central nervous system (CNS) disorders such as schizophrenia and epilepsy." (PMID 22350622, 2012).
glomerulosclerosis (1 paper, 2015). A hardening of the kidney glomerulus caused by scarring of the blood vessels. "The transgenic mice that had higher expression of mutant Actn4 exhibited significant albuminuria, glomerulosclerosis, and foot process enfacement at 10 weeks of age." (PMID 26301083, 2015). "They found that mice that are heterozygous for an Actn4 transgene but homozygous for UCHL1 KO (K256E-Actn4pod+/UCHL1−/−) exhibited significantly ameliorated albuminuria, glomerulosclerosis, and foot process enfacement at 10 weeks of age." (PMID 26301083, 2015).
Hypoalbuminemia (1 paper, 2016). The concentration of albumin in the blood circulation is below the lower limit of normal. "Moreover, the severity of proteinuria and hypoalbuminemia at an early stage distinguishes it from previously known disease-causing ACTN4 mutations." (PMID 27977723, 2016).
lung squamous cell carcinoma (1 paper, 2022). "The mRNA expression of ACTN4 evaluated by quantitative real-time PCR was a factor significantly associated with cancer-specific mortality in patients with stage I–II lung squamous cell carcinoma (HR, 2.68; 95%CI, 1.21–5.92)." (PMID 36139525, 2022).
mastitis (1 paper, 2021). Inflammation of breast tissue during lactation or postpartum due to an obstructed duct or infection. "The ACTN4 gene was identified as the DEG in mastitis vs. healthy samples of sheep milk by transcriptomic analysis." (PMID 34691146, 2021). "Furthermore, ACTN4 was identified as a hub gene in mastitis-related modules." (PMID 34691146, 2021).
meningitis (1 paper, 2018). A disorder characterized by acute inflammation of the meninges of the brain and/or spinal cord. "Notably, this strategy involving activated EGFR competing with F-actin for ACTN4 to disrupt the cytoskeleton is exploited not only by meningitic E. coli K1 and K2 strains, but also by meningitis-causing S. suis strains." (PMID 30687645, 2018).
meningococcal infection (1 paper, 2017). Infections with bacteria of the species neisseria meningitidis. "The distribution of CD147 and β2AR in control and Actn4-depleted HBMECs was then examined in the context of meningococcal infection." (PMID 28569760, 2017). "Given the central role of Actn4 in CD147–β2AR receptor clustering and in the formation of cellular protrusions on meningococcal infection, we investigated if Actn4 levels would modulate meningococcal adhesion to human endothelial cells." (PMID 28569760, 2017). "Consistently, CD147 and Actn4 were both enriched and colocalized at cell–cell junctions in non-infected endothelial cells, whereas meningococcal infection induced their massive recruitment to bacterial adhesion sites, where they colocalized with cortical actin." (PMID 28569760, 2017).
metastatic disease (1 paper, 2017). "In addition, comparison between M0 and M1patients demonstrated that cases with metastatic disease had greater ACTN4 mRNA expression (p = 0.0443)." (PMID 29197410, 2017).
ovarian adenocarcinoma (1 paper, 2014). An adenocarcinoma that arises from the ovary. "Moreover, the cytoplasmic accumulation of ACTN4 was associated with several malignancies and was linked with a bad prognosis, and an accumulative genomic gain of ACTN4 was associated with the formation of ovarian adenocarcinomas." (PMID 25215525, 2014).
prostate tumors (1 paper, 2022). "Nevertheless, a low level of ACTN4 is observed in the prostate tumors, while high ACTN4 expression inhibits the proliferation of the cancer cells." (PMID 36476259, 2022).
Sepsis (1 paper, 2022). Sepsis is defined as life-threatening organ dysfunction caused by a dysregulated host response to infection. "Studies reporting on the role of HDAC7/ACTN4 in sepsis or SIC are limited." (PMID 35756932, 2022). "In addition, HDAC7/ACTN4 was upregulated in monocytes in patients with sepsis." (PMID 35756932, 2022). "In combination with sepsis-related DEmiRNAs, HDAC7/ACTN4 was identified as a key transcriptional regulatory pair in the progression of SIC and in monocyte regulation." (PMID 35756932, 2022).
squamous carcinoma (1 paper, 2019). "Moreover, a number of extracellular signals, which cause reorganization of actin cytoskeleton, such as EGF, extracellular matrix proteins, and cytochalasin D also promote co-localization of ACTN4 with actin structures in epidermoid carcinoma cells A431." (PMID 31766144, 2019).
virus infection (1 paper, 2024). "Detailed analysis of both nanopore sequencing and MeRIP-seq using anti-m6A Abs revealed that m6A levels of ACTN4 mRNA were decreased after viral infection, and similar pattern of the m6A motifs (GGACH) (data not shown) was also obtained." (PMID 39289355, 2024).
cancer (62 papers, 2010 to 2025). A tumor composed of atypical neoplastic, often pleomorphic cells that invade other tissues. "A recent study revealed that UCEC is one of the two cancer types with the highest mutation rates in disulfidptosis-related genes, whereas mutations in the ACTN4 and MYH10 genes are closely linked to poor survival." (PMID 39931061, 2025). "Increased ACTN4 expression was directly associated with advanced cancer stage, an increased incidence of metastases and a short survival period globally." (PMID 39061201, 2024). "As a member of the α‐actinin family of actin crosslinking proteins, ACTN4 was up‐regulated in several types of cancer and implicated in the metastasis of cancer." (PMID 38764726, 2024). "Gene amplification of ACTN4 located on 19q13 is also significantly associated with metastatic potential in various types of cancer." (PMID 36139525, 2022). "The alpha-actinin 4 (ACTN4) was originally described as an actin-binding cytoskeletal protein associated with cancer cell motility." (PMID 36476259, 2022). "A previous study showed that siRNA suppression of ACTN-4 protein expression diminished cell protrusion associated with cancer invasion in colon cancer cells." (PMID 36139525, 2022). "ACTN4 belongs to the actin cross-linked protein family and has been revealed to elicit a cancer-promoting effect on the progression of malignancies." (PMID 36118078, 2022). "Since its original description as a protein associated with cancer invasion many attempts were made to correlate ACTN4 expression with cancer prognosis and the success of particular treatment regimes." (PMID 31766144, 2019). "Increased ACTN4 expression was directly associated with the advanced cancer stage, an increased incidence of metastasis, and poor overall survival period." (PMID 29197410, 2017). "Since then, ACTN4 has been reported to be associated with the progression and metastasis of many types of cancer, including breast, colorectal, pancreatic, lung, brain, bladder, and ovarian cancers and salivary gland carcinoma." (PMID 25885339, 2015). "Elevated levels of ACTN4 protein expression are found in a number of human cancers and associated with cancer malignancies and poor patient outcome." (PMID 25860875, 2015). "Univariate analysis by the Cox proportional hazards model showed that histological grade, vascular invasion, and CNI of ACTN4 were independent risk factors for cancer death." (PMID 24574362, 2014). "Vascular invasion (hazard ratio [HR]: 7.46; 95% confidence interval [CI]: 1.98–28.06) and CNI of ACTN4 (HR: 3.23; 95% CI: 1.08–9.68) remained as risk factors for cancer death in multivariate analysis." (PMID 24574362, 2014). "Our laboratory identified the ACTN4 gene product as an actin-bundling protein that was closely associated with cell movement and cancer invasion." (PMID 24574362, 2014). "Copy number increase (CNI) of ACTN4 has been associated with poor prognosis and metastatic phenotypes in various human carcinomas." (PMID 24574362, 2014). "This discovery is of particular interest due to ACTN4’s known association with the core actin structures of invadopodia in carcinoma cells, and the finding that ACTN4 gene knockdown in DU 145 (a well-know PCa cell line) leads to significant decrease of in vitro invasiveness." (PMID 38033786, 2023). "Also downregulated in this experiment, ACTN4, that belongs to the family of actin-binding proteins, when overexpressed has been associated with cancer development, aggressiveness, invasion and metastasis, sustaining cell proliferation, motility and EMT." (PMID 36500393, 2022). "Moreover, WASF2 promoted invasiveness of cancer cells by binding to actin cytoskeletal protein alpha‐actinin 4 (ACTN4), and ACTN4 was associated with β‐catenin to regulate the adherence and movement of cells." (PMID 35849030, 2022). "ACTN4 is closely associated with malignancy and cell survival in many cancers." (PMID 33363146, 2020).